ERG (ETS transcription factor ERG)
Diseases named in the same sentence as ERG in open-access papers (continued):
Sharing a sentence is not in itself a finding about the gene and the disease.
cancer (continued). "Our data support earlier findings that low expression of ERG appears to be a prerequisite, but not a sufficient condition, for high cancer levels of the e4-e2 TIC event." (PMID 21261984, 2011). "It should be noted that the values for the ERG probe in the expression array showed a modest variation between fusion-positive and fusion-negative cancers." (PMID 21814574, 2011). "Strikingly, the top-ranked gene – CRISP3 – showed a massive fold increase in ERG-positive carcinomas as compared to both non-malignant tissue and ERG-negative carcinomas, which led us to validate and study this candidate target further." (PMID 21814574, 2011). "Therefore, ERG and ETV1 gene status was available from 308 of the 322 patients with a PTEN score (662 TMA cancer cores)." (PMID 20104229, 2010). "The TMPRSS2:ERG fusion product can be found in 20% of prostatic intraepithelial neoplasia (PIN) adjacent to fusion positive cancer tissue but not in benign prostate tissue specimens or proliferative inflammatory atrophy (PIA)." (PMID 24281166, 2010). "The 308 patients were stratified into those that had an ERG or ETV1 gene rearrangement in their cancers (122 patients, 40%) and those that did not (186 patients, 60%)." (PMID 20104229, 2010). "It is evident from the figure that the majority of ERG-high cancers displayed decreased expression of EPB41L3 and increased expression of EPB41L4B, whereas most of the ERG-low carcinomas had expression levels of the two genes within the range of benign tissues." (PMID 20860828, 2010). "In a similar fashion, EPB41L1 expression was on average lower in ERG-high than ERG-low cancers, but in this case the difference was not statistically significant." (PMID 20860828, 2010). "The up-regulation and down-regulation of genes in the cancer cells could also be attributed to the activation of specific transcription factors such as ATF3, RUNX2, ERG, DLX1 (and DLX2) identified in the cancer cell transcriptomes." (PMID 20021671, 2009). "Higher levels of Hsp-27 staining were almost entirely restricted to cancers lacking ERG rearrangements (χ2 trend=31.4, P<0.001), although this distribution did not have prognostic significance." (PMID 19707199, 2009). "The LEF1-targeting O’PROTAC (LEF1 OP-V1) and the ERG-targeting O’PROTAC (ERG OP-C-N1) both employed a VHL E3 ligase ligand, effectively inducing target protein degradation in nanomolar concentrations in the tens and subsequently inhibiting cancer cell growth both in vitro and in vivo." (PMID 40507351, 2025). "However, as more cancers were studied, a lower percentage of TMPRSS2:ETV1 fusions were found compared to TMPRSS2:ERG fusions, suggesting that other 5′ partners might be involved." (PMID 40427154, 2025). "A comparison with clinico-pathological features revealed inverse correlations depending on the ERG fusion status: In ERG-negative cancers, high (3+) MTAP expression correlated with advanced pT stage, high Gleason grade, and early PSA recurrence (p < 0.0001 each)." (PMID 40554389, 2025). "However, our results suggest that the clinicopathological significance of ERG/SPINK1 status is different between TZ and PZ cancer cases, thereby suggesting the presence of different genetic alterations in the carcinogenesis and progression in both types of cancers." (PMID 35475132, 2021). "The data of this study suggest, however that SFRP4 protein measurement may result in clinically useful prognostic information in ERG negative cancer." (PMID 32677026, 2020). "It cannot be excluded that the immunohistochemistry protocol developed for this project was better suited to distinguish expression differences in cancers with somewhat lower expression levels such as in ERG negative cancers than in tumors with higher expression, such as in ERG positive cancers." (PMID 32143573, 2020).
cancer (continued). "Because YAP1 expression was also linked to a positive ERG status, it was not surprising to find that high nuclear and cytoplasmic YAP1 staining was linked to deletions of 8p, 10q (PTEN), 16q and 17p (p < 0.0001) if all cancers were jointly analysed." (PMID 32488048, 2020). "An ERG specific cellular microenvironment may be responsible for the particularly prognostic role of TFAP2D-expression in ERG negative cancers or the mitigation of it in ERG negative cancers." (PMID 32143573, 2020). "Therefore, many proteins are upregulated or downregulated in ERG positive cancer cells in comparison to ERG negative cancer cells or normal tissues." (PMID 33195694, 2020). "SFRP4 up-regulation was strongly linked to TMPRSS2:ERG rearrangement and ERG expression: Strong SFRP4 positivity increased from 5.6% and 6.3% (by IHC and FISH) in ERG negative cancers to 11.2% and 11.7% in ERG positive cancers (p < 0.0001 each)." (PMID 32677026, 2020). "The evaluation whether a relationship exists between deletions and the expression of proteins that are also ERG related must therefore be done in subgroups of ERG positive and ERG negative cancers." (PMID 32143573, 2020). "This also applied for subsets of ERG-negative and ERG-positive cancers (data not shown)." (PMID 32377272, 2020). "This is particularly due to its independent prognostic role in ERG-negative cancers." (PMID 32417965, 2020). "This held also true for ERG negative and ERG positive cancers (p ≤ 0.02)." (PMID 30823906, 2019). "Data from next generation sequencing studies demonstrate that such deletions are more prevalent than mutations of coding genes and many of these deletions have been linked to either ERG positive (i.e. PTEN and 3p13) or ERG negative cancers (i.e. 6q15 and 5q23)." (PMID 30899444, 2019). "This relationship was more prominent in ERG negative than in ERG positive cancers." (PMID 31043167, 2019). "Its prognostic impact is pronounced, however, in cancers lacking TMPRSS2:ERG fusion." (PMID 31452838, 2019). "Those associations between ROCK1 and most deletions were less common in ERG positive than in ERG negative cancers may be due to the different microenvironment in ERG positive cells." (PMID 31557128, 2019). "That the impact of BAP1 on proliferation was much stronger in ERG negative than in ERG positive cancer further supports the notion that ERG activation may interfere with functions of BAP1." (PMID 31903168, 2019). "This became particularly clear in ERG negative cancers (p<0.05 for all deletions)." (PMID 31557128, 2019). "A modified cellular microenvironment may serve as an explanation for the particularly strong prognostic role of SNW1 expression in ERG negative cancers." (PMID 31043167, 2019). "The hazard ratio for PSA recurrence after radical prostatectomy for strong versus negative PTPN12 expression was in the univariate model a weak 1.85 for all cancers and a moderate 2.50 in the ERG negative subset as compared with 6.01 for the Gleason grade at biopsy." (PMID 31606028, 2019). "Finding a link between all of these deletions and GSK3ß up-regulation – exclusively in the subset of ERG negative cancers – suggests that GSK3ß might contribute to genomic instability at least in the absence of ERG." (PMID 30899444, 2019). "However, subset analysis of ERG positive and ERG negative cancers revealed that the associations, with the exception of PTEN, were solely driven by ERG negative cancers (p ≤ 0.002 each)." (PMID 30899444, 2019). "Interestingly, one cancer sample had a high expression of ERG without any detectable TMPRSS2-ERG transcript." (PMID 31537872, 2019). "This also held true for the subgroups of ERG negative and ERG positive cancers." (PMID 31557128, 2019). "The results of this study suggest that BAP1 expression may represent a useful marker in ERG negative cancer." (PMID 31903168, 2019).
cancer (continued). "Because of the high sensitivity of the RT-PCR, the fusion transcript might be detected although only present in few copies and without overexpression of ERG, as seen both in benign and cancer samples." (PMID 31537872, 2019). "Two significantly enriched pathways in LUAD and their related DEmRNAs, namely transcriptional misregulation in cancer (TGFBR2, FLI1, ERG and SIX1) and central carbon metabolism (NTRK3 and SLC7A5), were speculated to play key roles in LUAD regulated by DEmiRNAs." (PMID 30761256, 2019). "This holds true for the subgroup of ERG fusion negative and positive cancer (data not shown)." (PMID 29855276, 2018). "However, subset analyses revealed that the prognostic impact of BCAR1 expression was limited to ERG-negative cancer." (PMID 29304771, 2018). "It is, thus, possible that post-transcriptional modifications may account for the different BCAR1 expression levels in ERG-positive and ERG-negative cancers, including for example altered protein stability." (PMID 29304771, 2018). "Our work delineates the role of ERG and FLI1 in ECs, and suggests that maintaining the expression of these TFs may be possible therapeutic options for various EndMT-related diseases including cancer." (PMID 30500808, 2018). "That associations between YB-1 and chromosomal deletions were markedly stronger in the subset of ERG-negative cancers may suggest a diminished impact of YB-1 on the DSB repair machinery in the presence of ERG fusion." (PMID 28515422, 2017). "There was a significant association between strong FAM13C staining and early PSA recurrence if all tumors were jointly analyzed (p < 0.0001; 6.1), and also if the subgroups of ERG negative (p < 0.0001) and ERG positive (p < 0.0001) cancers were analyzed separately." (PMID 28415558, 2017). "This held also true for ERG-negative, but not for ERG-positive, cancers." (PMID 28146062, 2017). "We reasoned that, as a transcriptional activator, ERG protein per se might not directly control cancer development." (PMID 27191272, 2016). "Comparison of homogenously 6q15 deleted cancers lacking focal ERG positivity (n = 16) and homogenously ERG-positive cancers with focal 6q15 deletion (n = 6 of 42) reaches no statistical significance (p = 0.129, data not shown) most likely due to the small number of cases with homogenous alterations." (PMID 26684029, 2016). "As for TDRD1 and PLA2G7, progression-associated overexpression of CACNA1D may be largely independent of ERG-status in these cancers, and apparently occurs also in ERG-negative cancers." (PMID 27196083, 2016). "All multivariate analyses revealed that 18q deletion predicted PSA recurrence independently in all scenarios (P ≤ 0.0004) and that the predictive value of 18q deletion was largely independent of the ERG status (P ≤ 0.02 in ERG-negative and P ≤ 0.065 in ERG-positive cancers)." (PMID 27861151, 2016). "However, our subgroup analyses demonstrated that the significant impact of SENP1 expression on outcome was entirely driven by the subgroup of ERG positive PTEN non-deleted cancers." (PMID 26202067, 2015). "However, for PTEN, the separate analysis of ERG-positive and ERG-negative cancers revealed a striking bimodal relationship with SOX9 expression." (PMID 26030748, 2015). "However, the inverse association between loss of SOX9 overexpression and PTEN deletion found in ERG-positive cancers indicates that very high SOX9 protein levels—as induced by ERG-fusion—might not per se provide a selection advantage to PTEN-deleted cancer cells." (PMID 26030748, 2015). "Data from next generation sequencing studies demonstrate that such deletions are more prevalent than any mutations of specific coding genes and many of these deletions have been linked to either ERG positive (i.e. PTEN and 3p13) or ERG negative cancers (i.e. 6q15 and 5q23)." (PMID 26230842, 2015). "Subgroup analysis for ERG-negative and positive cancers revealed similar results." (PMID 26230842, 2015).
cancer (continued). "In addition, tumors expressing ERG in patients with Gleason score 6 or 7 tumors had significantly shorter cancer specific survival than those with tumors lacking ERG expression." (PMID 24505269, 2014). "To determine whether the presence of ERG rearrangement was a prognostic factor for PCa, we compared cancer-related death rates between patients with or without ERG rearrangement." (PMID 24516518, 2014). "Interestingly, mitochondrial content was largely unrelated to all analyzed chromosomal deletions if all tumors were analyzed while there were reciprocal statistically significant findings in the subgroups of ERG positive and ERG negative cancers." (PMID 24261794, 2013). "Both ERG-positive and ERG-negative cancer cells were present in these tissues." (PMID 23390522, 2013). "Notably, subset analysis showed that the loss of p27 was correlated with low Gleason grades only in ERG fusion-negative cancers (P<0.0001) and not in ERG-positive tumors (P=0.5422) by IHC." (PMID 24179503, 2013). "The marked prognostic relevance of mitochondrial abundance found in the subset of ERG negative cancers may suggest “mitochondria content” as a biomarker with potential clinical utility." (PMID 24261794, 2013). "Mitochondrial content had a prognostic role in ERG negative but not in ERG positive cancers." (PMID 24261794, 2013). "In ERG negative cancers, most deletions (PTEN, 5q, 6q; p < 0.0001 each) were significantly associated with high mitochondrial content, while there was a tendency towards lower mitochondrial content in ERG positive cancers harboring deletions." (PMID 24261794, 2013). "Finally, a list of genes showed overexpression in TMPRSS2-ERG-negative carcinomas but an even more significant fold-increase in TMPRSS2-ERG-positive tumors, suggesting a role in malignant transformation in the prostate that is potentiated by ERG expression." (PMID 21814574, 2011). "We observed a massive fold-increase of CRISP3 in fusion-positive carcinomas as compared to non-malignant tissue or fusion-negative carcinomas and found that ERG genomic rearrangement and ERG and CRISP3 mRNA overexpression are associated with pT3 locally advanced tumors." (PMID 21814574, 2011). "Finally, a subgroup of genes showed significant fold-differences in ERG-negative carcinomas with an even more significant increase/decrease in ERG positive tumors." (PMID 21814574, 2011). "Interestingly, PTEN and ERG were not reported as cancer drug targets in DrugBank; thus, they may be candidates for therapeutic targeting." (PMID 39595075, 2024). "As the prognostic information derived from PSAP measurement was independent of established prognostic features in ERG-negative cancers, our data suggest that the quantification of PSAP protein levels may provide clinically useful information for this group of patients." (PMID 37892063, 2023). "Third, given that at least some other SFRP family members can have both suppressive or activating roles on Wnt signaling activity depending on their individual expression levels, it cannot be excluded that upregulated SFRP4 might have a Wnt activator role specifically in ERG-negative cancers." (PMID 32677026, 2020). "The strikingly higher SFRP4 expression in ERG positive (>30% with strong SFRP4 positivity) than in ERG negative cancers (<15% with strong SFRP4 positivity) could be explained by the transcriptional activation of ERG and its direct target EZH2, known reported as the upstream regulator of SFRP4." (PMID 32677026, 2020). "However, development of subpopulations with ERG fusions may be a much more frequent event in ERG negative cancer foci as previously believed." (PMID 27530104, 2016). "However, SENP1 was largely unrelated to all other deletions irrespective of whether all cancers or subgroups of ERG positive or ERG negative cancers were analyzed." (PMID 26202067, 2015).
cancer (continued). "However, HOXB13 was largely unrelated to all other deletions irrespective of whether all cancers or subgroups of ERG positive or ERG negative cancers were analyzed." (PMID 25825985, 2015). "ERG fusions found in 46 cases (226 cases without fusion, for 9 cases the fusion status is unknown) also confer a bad prognosis, yet the absence of a fusion is not a good indicator of an indolent evolution of the cancer." (PMID 24477410, 2014). "Furthermore TMPRSS2:ERG is unique only to prostatic nonbenign cancers." (PMID 23957008, 2013). "Differences may exist, however, in the biology of p27 in ERG fusion-negative and -positive cancers." (PMID 24179503, 2013). "In the PZ cancer group, a significant difference was not shown for the BCR‐free survival rate among the three subgroups, ERG‐/SPINK1‐, ERG‐/SPINK1+, and ERG+/SPINK1‐ (P = .39)." (PMID 35475132, 2021). "ERG-FISH and ERG-IHC showed highly concordant results: an identical finding (ERG-IHC positive and break by FISH or ERG-IHC negative and missing break by FISH) was found in 5256 of 5582 (94%) cancers." (PMID 32417965, 2020). "Expression of ESRPs was significantly linked to 11 (ESRP1)/9 (ESRP2) of 11 analyzed deletions in all cancers and to 8 (ESRP1)/9 (ESRP2) of 11 deletions in ERG-negative cancers portending a link to genomic instability." (PMID 33339518, 2020). "Most chromosomal deletions either preferentially occur in ERG-negative (5q, 6q, 13q, and 18q) or in ERG-positive (3p, 8p PTEN (10q23), 12q, 16, and 17p) cancers." (PMID 32377272, 2020). "Data on both ERG FISH and IHC were available from 5,976 cancers, and a concordant result (ERG IHC positive and break by FISH or ERG IHC negative and missing break by FISH) was found in more than 95% of the examined cancers." (PMID 31557128, 2019). "Data on both ERG FISH and IHC were available from 5,365 of these cancers, and an identical result (ERG IHC positive and break by FISH or ERG IHC negative and missing break by FISH) was found in 5,137 of 5,365 (95.8%) cancers." (PMID 30899444, 2019). "This was particularly evident for cancer samples with strong SNW1 expression, which was found in only 7% of ERG negative but in 24% of ERG positive cancers." (PMID 31043167, 2019). "This also hold true for the subsets of ERG-fusion negative and positive cancers as well as in the subset of PTEN deleted and PTEN wild type cancers (p<0.0001, data not shown)." (PMID 31557128, 2019). "Data on both ERG FISH and IHC were available from 5042 cancers, and an identical result (ERG IHC positive and break by FISH or ERG IHC negative and missing break by FISH) was found in 95% cancers." (PMID 29855276, 2018). "For example, high GGH staining was seen in 47.2% and 44.6% of cancers with TMPRSS2: ERG fusion detected by IHC and FISH, but was found in only 32.4% of cancers without ERG staining, and in 30.6% of cancers without ERG rearrangements (p < 0.0001 each)." (PMID 28146062, 2017). "8p deletions were marginally more frequent in ERG-positive cancers (40.9% according to IHC and 42.9% to FISH) than in ERG-negative cancers (34.7% according to IHC and 36.4% to FISH%)." (PMID 27880722, 2017). "It was present in 85% of ERG positive but in only 54% of ERG negative cancers (p < 0.0001), and in 91.1% of PTEN deleted but in only 69.2% of PTEN non-deleted cancers (p < 0.0001)." (PMID 28415558, 2017). "Our observation that 6 of 42 homogeneously ERG-positive cancer foci had focal 6q15 deletions strongly suggests, that presence of TMPRSS2:ERG fusions does not prevent the development of 6q15 deletions." (PMID 26684029, 2016). "HOOK3 immunostaining was seen in 74.3% and 76.1% of cancers with TMPRSS2:ERG fusion detected by IHC and FISH, but found in only 38.2% of cancers without ERG staining and 44.1% of cancers without ERG rearrangements detected by FISH (p<0.0001 each)." (PMID 26230842, 2015).